MMP9 (matrix metallopeptidase 9)
Diseases named in the same sentence as MMP9 in open-access papers (continued):
Sharing a sentence is not in itself a finding about the gene and the disease.
brain tumors (continued). "Furthermore, urinary NGAL and MMP-9 are useful predictors of the presence of brain tumors and may provide a basis for a novel, non-invasive method to identify new brain tumors and monitor known tumors after treatment." (PMID 19419554, 2009). "Urine samples from brain tumor patients showed significant elevations in MMP-2, MMP-9, MMP-9/NGAL, and VEGF compared to controls (all p < 0.001), with MMP-2 and VEGF providing the best diagnostic accuracy when combined." (PMID 40265458, 2025). "Recent studies have shown that MMP-2 and MMP-9 inhibition can enhance the penetration of chemotherapy drugs across the BBB, potentially improving their efficacy in treating brain tumors." (PMID 40265458, 2025). "MMP-9 plays a crucial role in GBM development and prognosis, and its inhibition has been shown to reduce the effects of GBM invasion in brain tumors." (PMID 40019229, 2025). "The protein expression of MMP9, MMP13, TIMP1, TIMP2, and TIMP4 was elevated in all three investigated brain tumor diagnoses." (PMID 38474106, 2024). "Excessive migration and invasion are characteristic of malignant brain tumors, and matrix metalloproteinases (MMPs), especially MMP2 and MMP9, play an essential role in the invasion of GBM cells." (PMID 36922509, 2023). "The role of MMP-9 in tumour tissue invasion and metastasis formation was already described in 1990, and the elevated levels of MMP-9 in human brain tumours was also been reported in the 1990’s." (PMID 36765669, 2023). "In particular, MMP-9/NGAL levels are elevated in tumor and urine samples of brain tumor patients, with a positive correlation between MMP-9/NGAL levels in the brain tumor and those in the urine." (PMID 26663949, 2015). "Evaluation of MMP-9 and MMP-9/NGAL complex in urine of patients with brain tumors revealed significantly higher expression levels compared with controls, which was also confirmed in tumor tissue." (PMID 23760084, 2013). "In this study, MMP-2, MMP-9, and MMP-9/NGAL, in addition to the pro-angiogenic molecule vascular endothelial growth factor (VEGF), were found to be elevated in the urine of 28 brain tumor patients relative to controls (p < 0.001)." (PMID 24400253, 2013). "Our data indicate that patients suffering from malignant, but not benign brain tumours can be distinguished from CTRL patients based on the MMP-9 level of serum sEVs, and that the MMP-9 level of serum sEVs differs between CNS tumour types, showing a positive correlation with tumour aggressiveness." (PMID 36765669, 2023). "We demonstrated on a large number of samples that the high MMP-9 level of serum-sEVs may serve as a negative prognostic marker for brain tumours." (PMID 36765669, 2023). "Interestingly, this study also found pro-MMP-9, the precursor of MMP-9, to be detectable in the CSF of all 39 brain tumor patients irrespective of CSF cytology status but in none of the controls." (PMID 24400253, 2013).
adenoma (30 papers, 1995 to 2025). A neoplasm arising from the epithelium. "Adenomas mutations were reviewed with a focus on adenoma-carcinoma transition and different subtypes, with MMP9 identified as the main metalloprotease implicated in tumor progression." (PMID 39022728, 2024). "Based on the up-regulation of this metalloproteinase as an early event in the adenoma-carcinoma sequence, some studies have centred on the diagnostic utility of MMP-9." (PMID 26264519, 2015). "Serum MMP9 levels are raised in those with cancer and high-risk adenomas, although MMP9 estimation is likely to have the greatest predictive utility when used as part of a panel of biomarkers." (PMID 22433968, 2012). "In the Apcmin/+ model, supplementation with KLK1 significantly inhibited adenoma formation, reduced epithelial dysplasia, and downregulated pro‐oncogenes such as Mmp2, Mmp9, Fap, Dcn, and Ctnnb1." (PMID 40859429, 2025). "Increased KLK1 expression led to decreased Mmp2 and Mmp9 levels and reduced adenoma formation, an effect inhibited by SSR240612." (PMID 40859429, 2025). "Some studies also indicated high expression levels of MMP-9 protein in adenomas with HGD compared to adenomas with LGD and normal tissue." (PMID 34944846, 2021). "MMP-9 proved to be significantly lower compared to either adenomas sized <1 cm with CRCs or adenomas sized ≥1 cm with CRCs (p ≤ 0.001 and p ≤ 0.001)." (PMID 27413251, 2016). "The corrected MMP-9 levels were also studied regarding the characteristics of adenomas (number of lesions per individual, size, histology and location)." (PMID 26264519, 2015). "Corrected MMP-9 (cMMP-9) levels were higher in individuals with advanced adenomas (AA; p-value = 0.029) and AN (p-value = 0.056) compared to individuals with no neoplasia." (PMID 26264519, 2015). "Our observations about MMP-9 levels in serum samples are in agreement with the progressive increase of tissue MMP-9 in the mucosa—adenoma—carcinoma multi-step process described by several authors." (PMID 26264519, 2015). "In relation to the location of adenomas, serum corrected MMP-9 levels were equivalent for the distal, proximal or distal and proximal colorectal lesions included in our study." (PMID 26264519, 2015). "A role for inflammatory neutrophil-derived gelatinase B/MMP-9 in intestinal adenoma initiation has been described in heterozygous APC (APC-min) knockout mice, with a 40% reduction in adenoma formation observed upon gelatinase B/MMP-9 knockout." (PMID 24473089, 2014). "Our group has also shown that protein expression of MMP-9 in CRC was significantly higher compared to adenomas and the normal mucosa." (PMID 23202950, 2012). "An intense immunoreaction was especially evident for MMP-2 in carcinomas, while the difference in MMP-9 immunolabelling in adenomas and carcinomas was lower." (PMID 21726449, 2011). "Increased levels of an enzyme called matrix metalloproteinase 9 (MMP9) has significant potential as a marker for both adenomas and cancers, and this can be measured from a blood sample." (PMID 19175925, 2009). "The analysis of colonic adenomatous nodes revealed low expression of all the explored acute colitis-associated key genes: the expression levels of C3, Tyrobp, Mmp3, Mmp9, and Timp1 in adenoma tissue were 26.3, 3.4, 20.8, 11.9, and 27.7 times lower than those in the samples with acute colitis." (PMID 36901742, 2023). "As such, researchers speculated that upregulation of MMP-9 is a primary event in the CRC adenoma-carcinoma sequence." (PMID 34944846, 2021). "We have also found that MMP-9 upregulation is an early event in the adenoma-carcinoma sequence and, therefore, MMP-9 might be a molecular marker for early colorectal carcinogenesis." (PMID 25948887, 2015).
adenoma (continued). "In the heterozygous APC knockout mouse model (APC-min), neutrophil-derived gelatinase B/MMP-9 stimulates adenoma initiating cell proliferation, promoting adenoma expansion, and implicating gelatinase B/MMP-9 in the expansion of tumour cell populations that lack full APC function." (PMID 24473089, 2014). "In addition, we demonstrated higher tissue expression of MMP-9 in adenomas with HGD compared to other adenomas or normal colonic mucosa." (PMID 23202950, 2012). "MMP9 has significant potential as a marker for both adenomas and cancers." (PMID 19175925, 2009). "However, MMP-9 proteolytic activity in the serum of patients with adenomas remained systematically in the same range as in healthy subjects, suggesting the interest of this biomarker in differentiating patients with precancerous lesions (adenomas) from those with CRC." (PMID 34298680, 2021). "In adenoma samples, dysplastic epithelial cells showed moderate intensive cytoplasmic MMP-9 expression, with a clear-cut differentiation between dysplastic and non-dysplastic areas, indicating that the overexpression of MMP-9 may be an early event in colorectal carcinogenesis." (PMID 23202950, 2012). "Stool fibrinogen, MMP-8, MMP-9, PGRP-S, haptoglobin, and myeloperoxidase emerge as promising biomarkers for distinguishing CRC/advanced adenomas/healthy stools, meeting or outperforming current yardsticks." (PMID 41033463, 2025). "Western blot experiments on adenoma specimens confirmed the upregulation of MAPK pathway proteins and MMP9." (PMID 38739004, 2024). "During adenoma-carcinoma development, a progressive increase in interleukin-8 (IL-8), CRP, and MMP-9 occurs." (PMID 29929486, 2018). "Our results are in agreement to the findings of Mroczko et al20 who revealed that serum concentrations of MMP-9 and TIMP-1 were significantly higher in adenoma patients compared to control group, but lower than in patients with CRC." (PMID 29201696, 2015). "The expression of MMP-9 and TIMP-1 in the normal mucosa-adenoma-dysplasia-adenocarcinoma sequence of the colon was studied by few authors." (PMID 23202950, 2012). "Pro-MMP-9 and pro-MMP-2 were significantly concentrated in the plasma of all of the dogs, and bands for the latent forms were present in both animals with adenoma and animals with carcinoma." (PMID 21726449, 2011). "Stool fibrinogen, MMP-9, hemoglobin, MMP-8, and PGRP-S were the top 5 stool proteins with the highest accuracy for distinguishing advanced adenoma from HC, with stool fibrinogen topping the list with a receiver operating characteristic area under the curve value of 0.86." (PMID 41033463, 2025). "In our study we found an increase in the corrected median MMP-9 serum concentration from individuals with no neoplasia—non-advanced adenomas—advanced adenomas (564 ng/mL–599 ng/mL–648 ng/mL)." (PMID 26264519, 2015). "An accompanied increase in MMP9 and VEGF, which could be blocked by pharmacologically inhibiting 5-LO, suggested that 5-LO expression in the inflamed colon may be involved in the angiogenic and inflammatory process of adenoma formation." (PMID 28125014, 2017). "Indeed, gelatinase B/MMP-9 degrades IGF-BPs augmenting the circulating levels of IGF, promoting astrocytoma growth, and increasing circulating VEGF and EGF levels, which also promote adenoma cell proliferation in APC-min mice." (PMID 24473089, 2014). "In this study, among neoplastic polyps, pro-MMP-9 activity was significantly higher in advanced versus non-advanced adenomas and in those harboring high-grade dysplasia (HGD), suggesting that MMP-9 might be a marker for early colorectal carcinogenesis." (PMID 23202950, 2012). "No bands were observed for the active form of MMP-9 in adenomas." (PMID 21726449, 2011). "However, neither FC nor fecal MMP-9 provided valuable information on the detection of adenomas." (PMID 27413251, 2016).
adenoma (continued). "We studied the features of the 174 adenomas included in our cohort (121 non-advanced and 53 advanced lesions) and found that the most severe characteristics such as 3 or more lesions, size ≥1 cm, and tubulovillous or villous histology corresponded to higher levels of corrected MMP-9, over 700 ng/mL." (PMID 26264519, 2015). "Both MMP-9 and TIMP-1 mRNA were observed in all ten liver metastases but were absent in three adenomas and in all normal colonic mucosa and liver." (PMID 7669564, 1995). "In addition, in nonfunctioning adenomas, interleukin 6 receptor (IL-6R)/Janus kinase 2 (JAK2)/STAT3/matrix metallopeptidase 9 (MMP9) and phosphatidylinositol 3-kinases (PI3K) have been discovered to be involved in the PI3K/AKT pathway." (PMID 40299639, 2025).
meningioma (30 papers, 2000 to 2025). A generally slow growing tumor attached to the dura mater. "Upon analyzing blood serum from four patient groups, including meningioma, the group confirmed increased sEV MMP-9 concentration is associated with decreased patient survival." (PMID 38673779, 2024). "Thus, the evaluation of both MMP-9 and PR expression might be of use in the identification of spinal meningiomas at higher risk of relapse." (PMID 25821815, 2015). "Other studies reported the important role of matrix metalloproteinases MMP-2 and MMP-9 in canine and human meningiomas, where they are involved in extracellular matrix degradation, required for tumor progression and recurrence." (PMID 38137885, 2023). "For example, the invasiveness and aggressiveness of meningiomas were related to an upregulation of MMP-9 and a downregulation of E-cadherin, AKAP-12, and DEP-1." (PMID 36077700, 2022). "Cytokines such as interleukin-6 can simulate substances such as VEGF-A and MMP-9, which are involved in the pathogenesis of peritumoral edema in meningioma." (PMID 34298854, 2021). "In terms of tumour recurrence, lower TGF-ß expression and higher expression of OPN, HGF/SF, MIP and MMP-9 were found to correlate significantly with the recurrence of meningiomas." (PMID 34503077, 2021). "Previous studies have shown that the expression of MMP-9 in meningioma is significantly correlated with the degree of malignancy and invasiveness." (PMID 33042832, 2020). "The data shown here indicate that tissue MMP-9 expression is significantly increased in atypical meningiomas compared to lower grade specimens, and is positively correlated with Ki-67 index levels." (PMID 27757720, 2017). "Modest MMP9 expression, similar to that observed in meningiomas, was observed in meningothelial cells; however, markedly increased expression was identified on the basal aspect of the meninges and in the immediately subjacent tumor." (PMID 27255663, 2016). "A survey of meningiomas from 10 patients demonstrated MMP9 expression in all of these, with higher levels of expression in more epitheloid tumors and in the epithelioid areas of tumors with mixed morphologies." (PMID 27255663, 2016). "In our present study, we also showed a significant correlation between MMP-9 and the presence of peritumoral brain edema; all of the meningiomas with presence of peritumoral brain edema showed strong MMP-9 expression." (PMID 25821815, 2015). "MMP-9 expression was significant mainly in meningiomas with PTBE evaluated as II or III stage in Steinhoff classification (38 and 2 cases, resp)." (PMID 25821815, 2015). "They concluded that MMP-2 and MMP-9 expression by tumor cells, evaluated through immunohistochemistry, is not predictive of the formation of peritumoral edema in canine rostrotentorial meningiomas." (PMID 25821815, 2015). "In the low grade meningioma group, MMP-9 expression was observed in 65 out of 93 cases (69.9%), mostly as weak expression estimated as (+)." (PMID 25821815, 2015). "In meningiomas, MMP-9 expression in tumors has been correlated with peritumoral brain edema and cell proliferation." (PMID 25821815, 2015). "Compared with the control group, MMP-9 was invariably and highly expressed in immunohistochemical staining of microcystic meningiomas." (PMID 25821815, 2015). "In the study, we showed significant MMP-9 expression in both low- and high-grade meningiomas; however, the most significant MMP-9 expression was observed in atypical and anaplastic meningiomas." (PMID 25821815, 2015). "They found increased MMP-9 expression in DEP-1-depleted meningioma cells using zymography, suggesting that up-regulation of MMP-9 may contribute to the aggressive growth of meningioma." (PMID 33042832, 2020). "A study of malignant meningioma cell lines found that the expression of MMP-9 was silenced by small interfering RNA (siRNA) which could inhibit the formation of a capillary network." (PMID 33042832, 2020).
meningioma (continued). "The expression of MMP-9 in different grades of meningiomas has also been studied." (PMID 33042832, 2020). "Another study showed increased expression of MMP-9 in meningioma cells following irradiation." (PMID 33042832, 2020). "In the high-grade meningioma group, 40 out of 43 cases (93.1%) presented MMP-9 expression." (PMID 25821815, 2015). "Furthermore, meningiomas which recurred or transformed into more malignant forms presented high MMP-9 expression." (PMID 25821815, 2015). "Our results suggest that the dosage of MMPs in the sera of CNS tumor patients and the immunohistochemical evaluation of MMP-9 and its correlation with Ki-67 only in meningiomas, might provide clinicians additional objective information on intracranial neoplasms." (PMID 27757720, 2017). "As we had previously validated meningiomas as a cell culture model system of the leptomeninges, we sought to determine whether MMP9 was expressed in human meningothelial-derived tumors by immunohistochemistry as a surrogate for reactive leptomeninges as might be present in medulloblastoma." (PMID 27255663, 2016). "KLF4K409Q tumours showed upregulation of CD44, a cell surface receptor interacting with matrix metallopeptidase 9 (MMP9) and positively correlated with proliferation, which is upregulated in higher-grade meningiomas." (PMID 40562609, 2025). "Meningiomas Group: ICAM-1, E-Selectin, and MMP-9 were the most expressed markers, while PAI-1 and VCAM-1 exhibited less expression." (PMID 38306519, 2024). "In the malignant meningioma cell lines IOMM-Lee and CH157-MN, MMP-9 has been shown to be significantly up-regulated with increased expression of the lncRNA LINC00460, leading to the progression of meningioma." (PMID 33042832, 2020). "Results of immunohistochemical analysis indicated that more MMP-9 was expressed in grade II and III meningiomas." (PMID 33042832, 2020). "Our findings point to asignificant role of MMP-9 and VEGF in the pathogenesis of peritumoral brain edema in low- and high-grade meningiomas." (PMID 25821815, 2015). "The aim of our study was to evaluate the expression of MMP-9 and VEGF in a large group of meningiomas of various grades in correlation with the extent of PTBE." (PMID 25821815, 2015). "Our study seems to prove the significant role of MMP-9 and VEGF expression in the pathogenesis of peritumoral brain edema in low- and high-grade meningiomas as well as in recurrence or malignant transformation." (PMID 25821815, 2015). "Previous studies have demonstrated that downregulation of MMP-9 not only reduced the invasive nature but also subsequently led to ERK and AKT-mediated apoptosis in meningioma and medulloblastoma cells." (PMID 23183822, 2012). "Previous studies have proposed an increased expression of SPARC (secreted protein, acidic and rich in cysteine) and matrix metalloproteinase-9 (MMP-9) as a sign of brain-invasive meningioma in the absence of an infiltrative interface with the brain." (PMID 34209798, 2021). "In atypical meningiomas, the MMP-9 expression was strong and some showed weak MMP-9 expression." (PMID 25821815, 2015). "That is why MMP-9 and VEGF may be useful prognostic factors for worse clinical outcome of meningiomas." (PMID 25821815, 2015). "It was validated that MMP-9 concentration in circulation is related to tumor aggressiveness and showed variation among tumor type and stage; however, it was not successful in distinguishing between control and meningioma patient groups." (PMID 38673779, 2024).